FGFR4 (fibroblast growth factor receptor 4)
Diseases named in the same sentence as FGFR4 in open-access papers (continued):
Sharing a sentence is not in itself a finding about the gene and the disease.
lymph node metastasis (6 papers, 2015 to 2023). "Increased FGFR3 expression enhanced the recurrence risk (hazard ratio 4.72, p = 0.029), while high FGFR4 expression was associated with lymph node metastasis (p = 0.036)." (PMID 36142417, 2022). "Only high FGFR4 expression was significantly associated with the following factors closely related to tumor growth: depth of invasion, lymph-node metastasis, tumor stage, and distant metastasis or recurrence." (PMID 28056982, 2017). "In DGC, high expression of FGFR1, FGFR2, or FGFR4 was significantly associated with the depth of invasion, lymph-node metastasis, pathological stage, and distant metastasis or recurrent disease." (PMID 28056982, 2017). "Furthermore, our study shows that the increased tumor mRNA expression of FGFR3 is an unfavorable prognostic factor in terms of the risk of recurrence for Sq-NSCLC patients and the increased FGFR4 mRNA level is correlated with lymph node metastasis occurrence." (PMID 36142417, 2022). "Additionally, the presence of at least one FGFR4 Arg388 allele was significantly associated with the presence of lymph node metastasis at the time of surgery." (PMID 27640814, 2016). "Fibroblast growth factor receptors were reported to have important roles in the tumor–stroma interaction, and FGFR4 was demonstrated to correlate significantly with tumor development and lymph node metastasis of colorectal cancer." (PMID 29038591, 2017). "A relationship between FGFR4 and lymph node metastasis has been implied." (PMID 36142417, 2022). "The expression of FGFR4 or SRC positively correlated with higher AJCC stages, lymph node metastasis, and distant metastasis." (PMID 36923538, 2023).
sarcoma (6 papers, 2015 to 2025). A usually aggressive malignant neoplasm of the soft tissue or bone. "Mutations in Fibroblast Growth Factor Receptor 4 (FGFR4) have also been described in paediatric sarcomas, most outstandingly in RMS." (PMID 33916788, 2021). "In pediatric sarcoma databases, the rates of alterations of the FGFR1, FGFR2, FGFR3, and FGFR4 genes were 1.3%, 0.2%, 0.2%, and 2.4%, respectively, while in neuroblastoma tumor samples, the rates of alterations were 0.2% for each." (PMID 40510032, 2025). "Whereas the inhibition of tyrosine phosphorylation of PDGFR and ERBB family members was a common event in roneparstat-treated cells from the different sarcoma histotypes, the drug interference on the activation of other receptors (i.e. IGF1R, FGFR4) was found to occur in a cell line-specific way." (PMID 27374103, 2016).
heart failure (5 papers, 2016 to 2025). Inability of the heart to pump blood at an adequate rate to meet tissue metabolic requirements. "Mechanistically, FGF23-mediated activation of FGFR4 causes mitochondrial dysfunction, suggesting that early pharmacologic inhibition of FGFR4 might serve as novel therapeutic intervention to prevent development of LVH and heart failure in patients with CKD." (PMID 38196615, 2023).
renal fibrosis (5 papers, 2019 to 2025). A final common manifestation of a wide variety of chronic kidney diseases characterized by glomerulosclerosis and tubulointerstitial fibrosis. "Indeed, FGF23/FGFR4 signaling is associated with muscle pathogenesis in the heart as well as renal fibrosis, processes that, if active in skeletal muscle, could explain the decline in muscle quality over time." (PMID 33876724, 2021). "The results revealed that Lgals3‐mediated lactate generation promoted lactylation at H3K18, which contributed to FGFR4 expression, and promoted CaOx kidney stone formation and renal fibrosis." (PMID 39903812, 2025). "The current study found that FGFR4 was significantly increased and is essential for Lgals3‐mediated CaOx crystal deposition and the development of renal fibrosis." (PMID 39903812, 2025). "Elevated Lgals3 interacted with PKM2 and promoted the expression of FGFR4 via H3K18la, thereby facilitating CaOx crystal deposition and the development of renal fibrosis." (PMID 39903812, 2025). "In summary, our present findings indicate that excessive FGF23 can promote renal fibrosis in type 2 CRS mice by binding to FGFR4 and activating β-catenin signaling pathway." (PMID 33460402, 2021). "We concluded that FGF23 promotes CRS-induced renal fibrosis mediated by partly activating FGFR4/β-catenin signaling pathway." (PMID 33460402, 2021). "FGFR4 antagonist BLU9931 also significantly inhibited MI-induced renal fibrosis." (PMID 33460402, 2021). "The role of FGFR4 in the process of renal fibrosis is not fully understood." (PMID 33460402, 2021). "Similarly, renal fibrosis was increased in all kl/kl mice and mRNA expression of markers of fibrogenesis such as Timp1, Col1a2 and Fn1 were elevated in kl/kl kidneys independently of the presence of FGFR4." (PMID 31575945, 2019). "However, in our mouse model of dietary induced CKD, we did not observe differences in TGF-β expression, renal fibrosis or markers of fibrinogenesis following FGFR4 deletion or gain of function mutation." (PMID 31575945, 2019). "Elevated Lgals3 interacted with PKM2 and promote the expression of FGFR4 via histone H3K18 lactylation, thereby facilitating CaOx crystal deposition and the development of renal fibrosis." (PMID 39903812, 2025). "Considering that FGF23 can bind with low affinity to FGFR1c, FGFR3c and FGFR4, we used a pan-FGFR inhibitor PD173074 to further test the effect of FGF23 on cardio-renal fibrosis." (PMID 33460402, 2021). "Although it remains unclear how much contribution of FGFR4 to renal fibrosis, our in vitro results confirmed that inhibition of FGFR4 significantly inhibited the profibrotic effect of FGF23, suggesting that FGF23-FGFR4 axis plays an important role in renal fibrosis." (PMID 33460402, 2021).
triple-negative breast carcinoma (5 papers, 2017 to 2025). An invasive breast carcinoma which is negative for expression of estrogen receptor (ER), progesterone receptor (PR), and human epidermal growth factor receptor 2 (HER2). "In vitro experiments with triple negative breast cancer cells (MDA-MB-231) demonstrated that cells expressing the FGFR4 Arg388 variant have increased motility compared with cells expressing the FGFR4 wide-type counterpart (Gly388)." (PMID 28445975, 2017). "FGFR4 mRNA was expressed at low levels in normal mammary epithelial cells (MCF-10A) and triple-negative breast cancer cell lines." (PMID 35562334, 2022). "Phosphoproteomic profiling across 18 triple-negative breast cancers (TNBC) and 1 luminal B PDX revealed considerable heterogeneity in kinase activation, but 1/3 of PDX exhibited enhanced phosphorylation of FGFR1, FGFR2 or FGFR4." (PMID 34344433, 2021).
astrocytoma (4 papers, 2022 to 2024). "In grade 2–3 astrocytoma, variations in FGFR4, KIT, NTRK2, and positive immunohistochemistry for ATRX and EGFR showed statistically significant results in univariate survival analysis." (PMID 38970209, 2024). "Nevertheless, a driving role of FGFR4 in astrocytoma malignancy has been suggested, supported by a correlation of FGFR4 protein expression with malignant progression." (PMID 35484633, 2022). "Other cell lines that have been utilized in GBM zebrafish xenograft model research include U343 (n = 2), U373 (n = 3), BTL1528 and FGFR4-KD, the ATCC® CRL-1718TM human astrocytoma cell line, D54-MG, DBTRG and SJ-GBM2, and the HS683 oligodendroglial cell line." (PMID 37400666, 2024).
cardiomyopathy (4 papers, 2014 to 2022). A disease of the heart muscle or myocardium proper. "Similarly, inhibition of FGFR4 is a potential approach that might be useful for the cardiomyopathy associated with CKD54." (PMID 35513431, 2022). "We provide genetic and biochemical evidence that dysregulation of Fgfr4, Hras and Map2k2 in the heart of Rreb1 heterozygous mice is deleterious leading to a cardiomyopathy that is reminiscent of the phenotype observed in Noonan-like RASopathies." (PMID 32938917, 2020). "Moreover, as studies indicate anti-FGFR4 therapy may be beneficial toward cardiomyopathy, our data suggest these same beneficial outcomes for inflammation, anemia, and skeletal muscle wasting would not apply." (PMID 35302487, 2022).
chronic obstructive pulmonary disease (4 papers, 2018 to 2022). A chronic and progressive lung disorder characterized by the loss of elasticity of the bronchial tree and the air sacs, destruction of the air sacs wall, thickening of the bronchial wall, and mucous accumulation in the bronchial tree. "We have recently shown that FGFR4 signaling is also activated in chronic obstructive pulmonary disease (COPD)." (PMID 32793609, 2020). "FGFR2 and FGFR4 belong to the fibroblast growth factor receptor family which has been shown to mediate pro-inflammatory signaling in the liver and airway epithelium in chronic obstructive pulmonary disease." (PMID 35012443, 2022).
head and neck cancer (4 papers, 2017 to 2025). A primary or metastatic malignant neoplasm affecting the head and neck. "FGFR4 has been widely studied in other malignancies, such as breast, prostate, colorectal, gastric, and head and neck cancers, where its overexpression and polymorphic variants, particularly rs351855, have been linked to tumor progression, therapy resistance, and poor prognosis." (PMID 40806692, 2025). "Beyond PA, FGFR4 has been extensively studied in other tumors, including breast, prostate, colorectal, and head and neck cancers." (PMID 40806692, 2025). "Of note, all but two recommendations for therapies with M3 evidence level, i.e., olaparib for the treatment of a head and neck cancer with FANCL mutation and ponatinib for the treatment of a FGFR4-amplified soft tissue tumor, failed clinical translation." (PMID 38136436, 2023).
Hypertension (4 papers, 2017 to 2026). The presence of chronic increased pressure in the systemic arterial system. "Variants FGFR2 rs199545667 and rs4752570, along with FGFR4 rs351855, showed significant associations with elevated blood pressure and hypertension prevalence." (PMID 41573461, 2025). "This review highlights current evidence linking Pi-induced FGF23 pathogenically to hypertension, with focus on FGF23 translocation to and FGFR4 signaling in the central nervous system as a potential mechanism and therapeutic target for hypertension associated with high Pi intake and CKD." (PMID 41683565, 2026). "Second, specific FGFR4 blockade can partially reverse LVH and cardiac fibrosis in 5/6 nephrectomized rats, without ameliorating renal function or affecting severe hypertension." (PMID 28512310, 2017).
liver cirrhosis (4 papers, 2015 to 2024). "In conclusion, the study findings show a significant association between FGFR4 polymorphisms and liver cirrhosis in HCC." (PMID 25860955, 2015). "We observed that genetic polymorphism in FGFR4 rs351855 (Gly/Arg and Arg/Arg) was associated with high risk (OR: 2.113, 95% CI: 1.188–3.831) of liver cirrhosis and markedly increased the AFP level in patients with HCC." (PMID 25860955, 2015). "A variant FGFR4 allele may be an indicator for HCC in liver cirrhosis, the AST/ALT ratio, and the AFP level." (PMID 25860955, 2015). "Our findings suggest that genetic polymorphism in FGFR4 rs351855 may be associated with the risk of HCC coupled with liver cirrhosis and may markedly increase the AFP level in Taiwanese patients with HCC." (PMID 25860955, 2015). "We concluded that FGFR4 SNPs at rs351855 can be a useful marker for predicting the liver cirrhosis status in HCC." (PMID 25860955, 2015). "Moreover, this is the first study that correlated liver cirrhosis, the AST/ALT ratio, and the AFP level caused by FGFR4 polymorphic variants and their association with HCC." (PMID 25860955, 2015). "Furthermore, the clinical status and FGFR4 genotypes in patients with HCC were evaluated to clarify the clinical role of FGFR4 polymorphisms in HCC, including the Child-Pugh grade, presence of an HBV or HCV infection, and liver cirrhosis." (PMID 25860955, 2015). "Liver cirrhosis status, virus status, and FGFR4 genotypic frequencies in 289 patients with HCC." (PMID 25860955, 2015). "FGFR4 rs351855 polymorphisms may lead to alterations in the coding sequence of the encoded protein, thereby impacting the initiation and/or progression in HCC, particularly in patients with liver cirrhosis." (PMID 25860955, 2015).
liver fibrosis (4 papers, 2015 to 2020). "Our in silico analysis implicated that FGFR4 was targeted by miR-7-5p, indicating that miR-7-5p might be involved in liver fibrosis." (PMID 32587612, 2020). "Deletion of FGFR4 and Fgf15 (murine orthologue of FGF19) leads to significant liver fibrosis compared with little mates, suggesting that the FGFR4/FGF19 axis has antifibrotic properties." (PMID 32587612, 2020). "FGFR4 was downregulated, but miR-7-5p was markedly enhanced in the liver samples as the degree of liver fibrosis rose." (PMID 32587612, 2020). "The liver-protective effect of FGFR4 becomes even clearer in the model of carbon tetrachloride-induced liver damage, where more significant liver fibrosis was observed in FGFR4 knock-out compared with wild-type (wt) mice." (PMID 30634399, 2019). "FGFR4 contributes to the limitation of the resultant liver fibrosis." (PMID 25860955, 2015).
lung adenocarcinoma (4 papers, 2007 to 2021). A carcinoma that arises from the lung and is characterized by the presence of malignant glandular epithelial cells. "Further large-scale prospective studies are required to verify the significance of FGFR4 genetic polymorphisms in lung adenocarcinoma." (PMID 32781755, 2020). "A further study is the association between various FGFR4 SNPs and FGFR4 expression levels in lung adenocarcinoma." (PMID 32781755, 2020). "In one lung adenocarcinoma specimen from a current smoker, we found a somatic heterozygous G to A mutation at nucleotide position 2041 in exon 16 of FGFR4." (PMID 17487277, 2007). "The data indicate that both FGFR4 SNPs rs2011077 and rs351855 may be associated with reduced presence of distant metastasis in Taiwanese patients with lung adenocarcinoma, especially those with the wild-type EGFR gene." (PMID 32781755, 2020). "In conclusion, the data suggest that FGFR4 SNPs may help in identifying patient subgroups at low-risk for tumor metastasis, among carriers of lung adenocarcinoma bearing wild-type EGFR." (PMID 32781755, 2020). "FGFR4 SNPs may help in identifying patient subgroups at low-risk for tumor metastasis, among carriers of lung adenocarcinoma bearing wild-type EGFR." (PMID 32781755, 2020). "The role of FGFR4 gene polymorphisms in the clinicopathological characteristics of lung adenocarcinoma in the Taiwanese cohort remains unclear." (PMID 32781755, 2020). "The present study examined the relationship between four single-nucleotide polymorphisms (SNPs; rs2011077 T/C, rs351855 G/A, rs7708357 G/A, and rs1966265 A/G) of FGFR4 and the risk of lung adenocarcinoma with the epidermal growth factor receptor (EGFR) mutation status in a Taiwanese cohort." (PMID 32781755, 2020). "Mutations observed in EGFR, KRAS, BRAF, and FGFR4 in lung adenocarcinomas." (PMID 17487277, 2007). "Our findings concerning FGFR4 SNPs rs2011077 and rs351855 may suggest a lower risk of tumor distant metastasis and FGFR4 gene expression levels may help the prediction of survival rates in Taiwanese lung adenocarcinoma patients, especially those bearing the wild-type EGFR gene." (PMID 32781755, 2020). "We found that patients in wild-type EGFR lung adenocarcinoma with higher FGFR4 expression had shorter overall survival times and five-years survival times compared with those with lower FGFR4 expression (p = 0.008; p = 0.006)." (PMID 32781755, 2020). "The potential mechanisms involved in dysregulated FGFR4 signaling cascades in Taiwanese patients with lung adenocarcinoma, particularly those with the wild-type EGFR gene, warrant further exploration." (PMID 32781755, 2020). "Using in silico analysis of the TCGA database, we found that lung adenocarcinoma patients bearing wild-type EGFR with the higher FGFR4 expression level is correlated with poor overall survival rates and five-years survival rates compared with those with lower FGFR4 expression patients." (PMID 32781755, 2020). "Furthermore, a database analysis using The Cancer Genome Atlas revealed that the higher FGFR4 expression level was correlated with poor survival rates in wild-type EGFR lung adenocarcinoma." (PMID 32781755, 2020). "Therefore, we examined the association between the FGFR4 SNPs and EGFR mutation in Taiwanese patients with lung adenocarcinoma." (PMID 32781755, 2020). "Our findings also implicate FGFR4 in the pathogenesis of a subset of lung adenocarcinomas." (PMID 17487277, 2007). "The FGFR4 mutation is analogous to a reported tumor-specific somatic mutation in ERBB2 and is located in the same exon as a previously reported kinase domain mutation in FGFR4 (Pro712Thr) in a lung adenocarcinoma cell line." (PMID 17487277, 2007). "Furthermore, we studied the effect of FGFR4 SNPs on the clinicopathological characteristics of lung adenocarcinoma with and without EGFR mutation." (PMID 32781755, 2020).
lung adenocarcinoma (continued). "The results demonstrated that FGFR4 rs2011077 (odds ratio (OR) = 0.348, 95% confidence interval (CI) = 0.136–0.891, p = 0.024), and rs351855 (OR = 0.296, 95% CI = 0.116–0.751, p = 0.008) showed an inverse association with distant metastasis in wild-type EGFR lung adenocarcinoma." (PMID 32781755, 2020). "We present the first portrait of clinically actionable alterations in lung adenocarcinoma of Indian origin that includes EGFR, KRAS, EML4-ALK, AKT1, PIK3CA, FGFR4 and ERBB2, similar to that identified in other ethnic groups, and an additional subset of patients with FGFR3 mutations." (PMID 27998968, 2017). "In the present study, we found no significantly different frequencies of the FGFR4 SNPs rs2011077, rs351855, rs7708357, and rs1966265 in patients with wild-type EGFR and mutant-type EGFR lung adenocarcinoma." (PMID 32781755, 2020).
oral squamous cell carcinoma (4 papers, 2017 to 2021). "However, the association between FGFR4 single-nucleotide polymorphisms (SNPs) and risk of oral squamous cell carcinoma (OSCC) remains to be determined." (PMID 29221201, 2017). "Examples are FGFR4 rs351855 in HCC, FGFR4 SNP rs2011077 with rs1966265 in urothelial cell carcinoma, and FGFR4 rs2011077 and rs1966265 in oral squamous cell carcinoma." (PMID 33981224, 2021). "In conclusion, the present study demonstrates that melatonin suppresses oral squamous cell carcinomas invasion and migration through blocking FGF19/FGFR4 pathway." (PMID 34576070, 2021).
thyroid cancer (4 papers, 2012 to 2020). "They identified upregulation of FGFR4 in aggressive thyroid cancer, compared to normal thyroid tissue using immunohistochemical analysis." (PMID 31408968, 2019). "Previous studies about the expression of FGFRs in thyroid cancer identified the upregulation of FGFR1 or FGFR4 in thyroid cancers, compared to normal tissues." (PMID 31408968, 2019). "Interestingly, a recent study focused on the role of FGF19/FGFR4/KLB signaling pathway in the development of thyroid cancers with upregulation of serum levels of KLB, FGF19, and FGFR4 in patients with thyroid cancer, compared to healthy controls." (PMID 31408968, 2019). "FGFR1 and FGFR3 are expressed in well-differentiated thyroid cancers, and ATC cells overexpress FGFR4." (PMID 25295214, 2014).
bronchopulmonary dysplasia (3 papers, 2019 to 2020). Bronchopulmonary dysplasia is a chronic respiratory disease that results from complications related to lung injury during the treatment of infant acute respiratory distress syndrome in low-birth-weight premature infants or from abnormal lung development in older infants. "Bronchopulmonary dysplasia, a pulmonary disorder of the newborn and associated with hyperoxia-induced lung injury, is also significantly linked with a polymorphism in the FGFR4 gene." (PMID 32793609, 2020).